CXCL11 (C-X-C motif chemokine ligand 11)
Diseases named in the same sentence as CXCL11 in open-access papers (continued):
Sharing a sentence is not in itself a finding about the gene and the disease.
glioblastoma (5 papers, 2023 to 2025). The most malignant astrocytic tumor (WHO grade IV). "In contrast, it has recently been shown in glioblastoma, that CXCL11 had a potent antitumor effect and reprogrammed the immunosuppressive tumormicroenvironment." (PMID 38609887, 2024). "CAR-T cells loaded with CXCL11-armed oAds to achieve sustained inhibition of glioblastoma (GBM) growth when combined with intratumoral administration." (PMID 38104104, 2023). "Systemic delivery of oncolytic viruses in glioblastoma (GBM) has been challenging; however, encapsulating CXCL11-modified oncolytic adenovirus with tannic acid and Fe3+ has extended circulation time and reshaped the tumor immune microenvironment effectively." (PMID 41050070, 2025). "In an immunodeficient and immunoreactive in situ GBM (glioblastoma) mouse model, B7H3-targeted CAR-T cells showed a durable anti-tumor response after intratumoral administration in combination with CXCL11-OADs." (PMID 38919533, 2024).
Granuloma (5 papers, 2015 to 2025). A compact, organized collection of mature mononuclear phagocytes, which may be but is not necessarily accompanied by accessory features such as necrosis. "Previous research indicates that mycobacterial infection induces the release of chemokines like CXCL10 and CXCL11, crucial for immune mediator formation and granuloma development in TB-specific T cells." (PMID 40463504, 2025). "Previous studies indicated that IFNγ mediates expression and secretion of chemokines CXCL9, CXCL10, and CXCL11 in macrophages, resulting in the recruitment of CXCR3 bearing CD4+ Th cells and CD8+ Tc cells into the lung and granuloma formation in humans and mice." (PMID 39464896, 2024). "The expression levels of CXCL10, CXCL11, CCR7, CCL17 and CCL18 in the tuberculous granuloma were measured by quantitative real-time RT-PCR and were compared with the levels detected in lung tissues without granulomas." (PMID 26091535, 2015).
osteosarcoma (5 papers, 2017 to 2023). A usually aggressive malignant bone-forming mesenchymal neoplasm, predominantly affecting adolescents and young adults. "We found that IHC staining exhibits that all the protein expression of CXCL9, CXCL11/CXCR3 axis was significantly elevated in osteosarcoma tissues compared with adjacent normal tissues (bone, marrow, soft tissue and cartilage)." (PMID 32820615, 2020). "The expression of BNIP3, SLC38A5, CKMT2, CXCL11, SLC5A3, S100A3, and PGM1 genes was verified in osteosarcoma cells (Saos-2 and 143B) and normal osteoblasts (hFOB1.19)." (PMID 36578780, 2022). "This study provides the clinical insight that chemokine signaling pathway genes (CCL21, CCL22, CCL24, CXCL11, CXCL12, CXCL13, GNAI2, and RAC2) in proliferating cells might be the potential biomarkers for treatment of osteosarcoma." (PMID 37537613, 2023).
chronic hepatitis C (4 papers, 2007 to 2019). "Various organ/tissue-specific diseases caused by increased inflammation, such as chronic hepatitis C virus infection, biliary cirrhosis, psoriatic and osteoarthritis, attract NK cells via the CXCR3/CXCL10 axis; meanwhile, CXCL11-targeted CXCR3 promotes antitumor responses." (PMID 31647037, 2019). "Furthermore, CCL3, CCL4, CCL5, CXCL9, CXCL10 and CXCL11 were found to increase in both liver and peripheral blood during chronic hepatitis C in several studies." (PMID 29284412, 2017). "In acute HCV infection, the increases in CXCL9, CXCL10, and CXCL11 with ALT levels follow a similar pattern, while their intrahepatic expression is correlate with liver inflammation and fibrosis in chronic hepatitis C." (PMID 24976843, 2014).
dengue (4 papers, 2007 to 2025). "Moreover, serum levels of IL-15, CCL-2, CXCL-10, and CXCL-11 correlated with dengue severity in humans." (PMID 40934228, 2025). "Although all three ligands are induced by dengue virus infection, CXCL9 and CXCL11 could not compensate for the absence of CXCL10 in Cxcl10-/-mice." (PMID 24939012, 2014).
heart failure (4 papers, 2021 to 2024). Inability of the heart to pump blood at an adequate rate to meet tissue metabolic requirements. "Its function can be regulated by cytokines, such as IFNγ and TNFα, and it has been proposed, together with CXCL9 and CXCL11, as a biomarker for heart failure and left ventricular dysfunction." (PMID 36364913, 2022). "Additionally, they used the levels of CXCL9, CXCL10, and CXCL11 in their study to adjust the prediction in the heart failure model, finding that including CXCL9, CXCL10, and CXCL11 improved the prognosis prediction of heart failure." (PMID 39726944, 2024). "In addition, the expression levels of CXCL11 and OLR1 have been proved to be elevated in heart failure patients." (PMID 37268658, 2023).
Hypertension (4 papers, 2011 to 2025). The presence of chronic increased pressure in the systemic arterial system. "A higher frequency of CD57+CD28−CD8+ T cells and increased expression of CXCL11 has been noted in patients with hypertension compared to healthy controls, suggesting that immunosenescent cytotoxic CD8+ T cells are linked to hypertension." (PMID 37174697, 2023). "A higher frequency of CD57+CD28−CD8+ T cells as well as increased expression of CXCL11 has been reported in the patients with hypertension compared to healthy controls, suggesting a role for immunosenescent proinflammatory cytotoxic CD8+ T cells in hypertension." (PMID 36059478, 2022).
inflammatory bowel disease (4 papers, 2013 to 2022). A spectrum of small and large bowel inflammatory diseases of unknown etiology. "CXCL9, CXCL10 and CXCL11 can activate T cells by binding to C-X-C motif chemokine receptor (CXCR) 3 and have been implicated in a variety of autoimmune diseases, including thyroiditis, systemic sclerosis, and inflammatory bowel disease (IBD)." (PMID 35464480, 2022). "CXCL11, referred to as interferon-inducible T-cell alpha chemoattractant (I-TAC), could drive Th1 cells to secrete proinflammatory cytokine IL-6 in the inflammatory bowel disease." (PMID 36003333, 2022). "CXCR3 and its ligands CXCL9, CXCL10, and CXCL11 are differentially elevated in many instances, such as with periodontal, autoimmune liver diseases, multiple sclerosis, bronchiolitis, skin or mucosal inflammation, cyclophosphamide (CYP)-induced cystitis, and inflammatory bowel disease (IBD)." (PMID 24278169, 2013).
leukemia (4 papers, 2019 to 2022). A malignant (clonal) hematologic disorder, involving hematopoietic stem cells and characterized by the presence of primitive or atypical myeloid or lymphoid cells in the bone marrow and the blood. "Strikingly, PDLS recapitulated the hypoxic CXCL11+ zones that support LICs, revealing the previously undescribed relevance of CXCL11+ mesenchymal niches for cell maintenance of long-term leukemia initiating and relapse population." (PMID 34737747, 2021). "In order to assess our transcriptional observations in our PDLS system, we used immunostaining approaches to characterize CXCL11 expression in a leukemia microenvironment." (PMID 34737747, 2021). "The transcriptional profiles of MSC reveal two characteristic signatures: a CXCL12-low inflammatory and leukemia expansion-like niche that likely supports leukemic burden and a CXCL11 high immune-suppressive and leukemia-initiating cell (SLIC)-like niche, where LICs are likely sustained." (PMID 35201533, 2022). "CXCL10hiCXCL11hi zones may represent exclusive leukemia-positioning niches where B-ALL cells may also contribute to CXCL11 expression presumably relevant for positioning of CXCR3+CXCR7+ LICs and suitable for immune scape." (PMID 34737747, 2021). "Taken together, we have implemented a novel PDLS system that enriches and supports leukemia cells with stem cell features driven by CXCL11+ MSCs within hypoxic microenvironments capable of recapitulating key features, such as tumor reemergence after exposure to chemotherapy and tumor initiation." (PMID 34737747, 2021). "As we know, CXCR3’s ligands included CXCL10 (IP-10) and CXCL11 (I-TAC), and few researches about CXCL9.CXCL10 was selected through stimulating leukemia U937cell lines from the DNA pool by Luster who comes from American." (PMID 30973890, 2019).
liver fibrosis (4 papers, 2015 to 2020). "It has been shown that the IFN- γ inducible chemokines CXCL9, CXCL10, and CXCL11 are up-regulated in patients with chronic liver diseases, and their serum levels are closely associated with the degree of hepatic fibrosis." (PMID 32887613, 2020). "Astonishingly, these findings are in line with seminal reports demonstrating that CXCL1, CXCL11, HIF1A, COL4A1, and FN1 are implicated in liver fibrosis." (PMID 32161843, 2020). "In a recent article published by our group, we found that CXCL9 rs10336 AA, CXCL10 rs3921 CC and CXCL11 rs4619915 AA genotypes were related to higher likelihood of severity of liver fibrosis in HIV/HCV-coinfected patients under a recessive model." (PMID 28755163, 2017). "Cytokines CXCL-11, INF-γ, and IL-17A are associated with liver inflammation, whereas CXCL-10, IL-2R, TGF-α, and IL-8 are correlated with liver fibrosis in chronic HBV-infected patients." (PMID 26559292, 2015).
mesothelioma (4 papers, 2016 to 2022). A usually malignant and aggressive neoplasm of the mesothelium which is often associated with exposure to asbestos. "In a mesothelioma mouse model, a tumor-selective oncolytic vaccinia virus expressing CXCL11 reportedly enhanced tumor infiltrating CTLs and NK cells, but not CD4+ T cells, and prolonged survival." (PMID 33777950, 2021). "Also, in the syngeneic mouse mesothelioma model, direct intratumoral delivery of a CXCL-11 armed vaccinia OV strain resulted in an elevation in anti-tumor cytotoxic T cell infiltration." (PMID 35488303, 2022).
prostate carcinoma (4 papers, 2015 to 2024). A carcinoma that arises from epithelial cells of the prostate gland. "Recent researches showed that miR-206 was down-regulated in PTC and miR-206 inhibits proliferation and migration process in prostate cancer by targeting CXCL11, which corresponded with our result." (PMID 38112616, 2023). "In prostate cancer, Andrographolide has been known to inhibit cell viability and cell migration by modulating CXCL11, CXCR3, CXCR7, and IL-16 expression." (PMID 30800220, 2019). "We thus reasoned that the CXCL11/CXCR7 axis may also engage the AR signaling pathway in human prostate-cancer cells." (PMID 25884570, 2015). "Several C-X-C motif (CXC) chemokines were upregulated in prostate cancer lung metastases, notably CXCL10, CXCL11, and CXCL13." (PMID 39146303, 2024). "Overall, these findings demonstrate that acute stimulation by chemokines CXCL11 and CXCL12 influences intracellular protein metabolism and/or protein trafficking in AD-LNCaP prostate-cancer cells." (PMID 25884570, 2015). "Together, these data showed that acute stimulation by chemokines CXCL11 and CXCL12 changed the intracellular immunoreactivity of CXCR4 and CXCR7 in AD-LNCaP prostate-cancer cells." (PMID 25884570, 2015). "CXCL10 and CXCL11 as well as CXCR3 are upregulated in lymph node-positive primary prostate cancer in comparison to lymph node-negative prostate cancer." (PMID 39146303, 2024). "More importantly, CXCL11 and CXCL12 were able to attenuate the expression of endogenous ARGs, demonstrating crosstalk between chemokine/chemoreceptor pathways and AR-mediated gene expression programs in prostate-cancer cells." (PMID 25884570, 2015).
renal cell carcinoma (4 papers, 2016 to 2024). "Sporadic instances of renal cell carcinomas in humans exhibit heightened expression levels of CXCL9, CXCL10, and CXCL11, hence facilitating the recruitment of T cells that possess CXCR3 and CCR5 receptors." (PMID 38730579, 2024). "In renal cell carcinoma (RCC), it was reported that high‐dose IL‐2 treatment in 20 patients elevated the plasma levels of CXCR3 ligands (CXCL9, CXCL10, and CXCL11), sequentially, forming an angiostatic environment." (PMID 27726306, 2016). "Interestingly, FYN, LRSAM1, IL20RB, CXCL11, S100A1, and MAP3K14 are also well-recognized biomarkers in the prognosis of renal cancer, which is reminiscent of the pancreatic metastasis from renal cell carcinoma in some earlier studies." (PMID 36428747, 2022). "Renal cell carcinoma, a typical immune-excluded tumor, is considered to lack the expression of some chemokines related to T cell recruitment, such as CXCL9, CXCL10, CXCL11, CXCL13, CX3CL1, CCL2, and CCL5, in its TME, but the specific mechanisms underlying this lack of chemokines remain unclear." (PMID 36397015, 2022).
tuberculosis (4 papers, 2012 to 2022). A chronic, recurrent infection caused by the bacterium Mycobacterium tuberculosis. "Both immunohistochemical staining and qRT-PCR indicated that the expressions of IL-27, CXCL9, CXCL10, and CXCL11 were significantly increased in tuberculosis patients, and IL-27 was significantly correlated with CXCL10 (r = 0.68)." (PMID 35785034, 2022). "In this study, we used immunohistochemistry to detect the expression levels of IL-27, CXCL9, CXCL10, and CXCL11 in patients with tuberculosis and observe their expression in the lesion." (PMID 35785034, 2022).
type 1 diabetes (4 papers, 2018 to 2022). "We further demonstrated increased serum levels of CXCL11 in adults with type 1 diabetes, irrespective of time from diagnosis." (PMID 29881878, 2018). "A disease-relevant synergy may therefore exist in the setting of type 1 diabetes among raised levels of BAFF, CXCL10 and CXCL11." (PMID 29881878, 2018). "Future studies will focus on investigating the ability of B cells from individuals with type 1 diabetes to migrate in response to physiological levels of CXCL10 and CXCL11, in the presence and absence of BAFF." (PMID 29881878, 2018).
viral meningitis (4 papers, 2007 to 2024). Inflammation of the membranes surrounding the brain and spinal cord due to a viral infection. "Yet, the combined data imply that CXCL11 might be a hallmark of viral meningitis." (PMID 30777092, 2019). "CSF concentrations of CXCL13 were significantly elevated in patients with CIS-RRMS, Lues, LNB, and bacterial and viral meningitis, CXCL11 CSF concentrations in all patients groups except CIS/RRMS and SPMS." (PMID 31727097, 2019). "However, elevated levels of CXCL11 in cerebrospinal fluid have been shown in patients with some neuro-inflammatory diseases such as bacterial and viral meningitis." (PMID 39062786, 2024). "Also, in viral meningitis, multiple cytokines (16/36) were elevated and we could confirm previously reported results for CXCL9, CXCL11, and IFNγ." (PMID 31727097, 2019).
AIDS (3 papers, 2021 to 2025). A syndrome resulting from the acquired deficiency of cellular immunity caused by the human immunodeficiency virus (HIV). "Our previous study showed that CXCL9 and CXCL11 levels were significantly increased in primary HIV infection, which was correlated with viral load and AIDS progression." (PMID 34447368, 2021).
Arthritis (3 papers, 2019 to 2023). Inflammation of a joint. "Similarly, pharmacological inhibition of the LPA1 receptor by Ki16425 in the K/BxN serum-transfer arthritis model led to a reduction in arthritis severity by decreasing cartilage damage, bone erosion, and expression of RANKL, ITAC/CXCL11, Pro-MMP9, and MMP3, in mouse arthritic joints." (PMID 35408784, 2022).
bladder cancer (3 papers, 2021 to 2023). "In addition, they also found that the expression of CXCL11 was predictive of chemotherapy response in human bladder cancer." (PMID 34692520, 2021).
chronic hepatitis B (3 papers, 2014 to 2022). "These cases suggest that the increase in the serum levels of CXCL9, CXCL10, CXCL11, and CXCL13 were associated with attaining an HBsAg loss in children with chronic hepatitis B." (PMID 37206604, 2020).
clear cell renal cell carcinoma (3 papers, 2019 to 2024). "Moreover, in clear cell renal cell carcinoma (ccRCC) tissue, RNA-binding motif protein 15 promoted M2 polarization by enhancing the stability of CXCL11 mRNA in an m6A-dependent manner, which resulted in ccRCC progression." (PMID 39548525, 2024). "It had been reported that the calculated score based on the expression of CXCL11, CXCL9, and CXCL10 could stratify nonmetastatic clear-cell renal cell carcinoma (ccRCC) patients into different risk subgroups." (PMID 31781593, 2019).
encephalitis (3 papers, 2017 to 2025). An acute inflammatory process affecting the brain parenchyma. "Encephalitis and meningitis patients differed with respect to other chemokines (CXCL11) and MMPs (MMP-3, MMP-8, MMP-9, and MMP-12), indicating that different location of the virus gives rise to qualitative differences in the ensuing inflammatory response." (PMID 30777092, 2019). "CCL19, CXCL8, CXCL9, and CXCL10 were significantly increased compared to CSF from control patients and compared to levels in serum in patients with encephalitis, meningitis, and Ramsay Hunt syndrome whereas CXCL11 was only increased in CSF in VZV meningitis patients." (PMID 30777092, 2019). "Whether CXCL11 and CCL8 are universal markers of meningitis but not encephalitis, or if HSV-1 and HSV-2 differ in their ability to induce the production of these chemokines, remains to be determined." (PMID 28693588, 2017).
endometriosis (3 papers, 2019 to 2024). The growth of functional endometrial tissue in anatomic sites outside the uterine body. "I-TAC/CXCL11 is a proinflammatory chemokine and increased blood levels have been found in FM and in endometriosis patients." (PMID 38304854, 2024).
gastritis (3 papers, 2010 to 2020). Inflammation of the stomach. "H. pylori-infected individuals with uncomplicated gastritis showed a significantly elevated expression of mRNA for both M1 (iNOS, 8-fold; CXCL11, 20-fold) and M2 markers (CCL17, 30-fold; CCL18, 70-fold, CD206, 2-fold) compared to uninfected volunteers." (PMID 21124899, 2010). "However, individuals with atrophic gastritis (4/6 had intestinal metaplasia in addition to atrophy) expressed even higher levels of iNOS mRNA compared to those with uncomplicated gastritis (20-fold), whereas CXCL11 and markers of M2 polarization were similarly expressed." (PMID 21124899, 2010).
liver cirrhosis (3 papers, 2017 to 2021). "CXCL10, CXCL11, CCL3, CCL4 and liver cirrhosis were the predictive factors for non-NR by univariate logistic analysis, but only the CCL4 was the independent predictor for non-NR by multivariate logistic analysis." (PMID 29284412, 2017). "By univariate logistic regression analysis, rs12979860 CC genotype, CXCL10, CXCL11, CCL3, CCL4 and liver cirrhosis were the factors for non-NR." (PMID 29284412, 2017).
macrophage activation syndrome (3 papers, 2021 to 2022). A complication of rheumatic disease that is caused by excessive activation and uncontrolled proliferation of T lymphocytes and well-differentiated macrophages. "Increased levels of IFNγ-induced chemokines such as CXCL9, CXCL10, and CXCL11 were found to be associated with sJIA complicating macrophage activation syndrome." (PMID 35268506, 2022). "The cytokine profile in these studies is comparable to that reported in cytokine release syndromes, such as macrophage activation syndrome, which is characterized by increased expression of cytokines (IL6, IL7, and TNF) and inflammatory chemokines (CCL2, CCL7, CXC-10, and CXCL-11)." (PMID 35145507, 2021). "In particular, the levels of CXCR9, CXCL10, CXCL11, and IL–18 were elevated in SJIA patients with macrophage activation syndrome compared with active SJIA without macrophage activation syndrome." (PMID 34884842, 2021).
meningitis (3 papers, 2017 to 2025). A disorder characterized by acute inflammation of the meninges of the brain and/or spinal cord. "High levels of CXCL9 and CXCL10 are detected in CSF of herpes simplex encephalitis and meningitis patients, whereas CXCL11 is exclusively found in herpes simplex meningitis patients." (PMID 30777092, 2019).